EMC7 (ER membrane protein complex subunit 7)
Description:
Part of the endoplasmic reticulum membrane protein complex (EMC) that enables the energy-independent insertion into endoplasmic reticulum membranes of newly synthesized membrane proteins. Preferentially accommodates proteins with transmembrane domains that are weakly hydrophobic or contain destabilizing features such as charged and aromatic residues. Involved in the cotranslational insertion of multi-pass membrane proteins in which stop-transfer membrane-anchor sequences become ER membrane spanning helices. It is also required for the post-translational insertion of tail-anchored/TA proteins in endoplasmic reticulum membranes. By mediating the proper cotranslational insertion of N-terminal transmembrane domains in an N-exo topology, with translocated N-terminus in the lumen of the ER, controls the topology of multi-pass membrane proteins like the G protein-coupled receptors. By regulating the insertion of various proteins in membranes, it is indirectly involved in many cellular processes (Probable).
Synonyms: C11orf3; C15orf24; HT022; ORF1-FL1
Tractability: Small molecule: a structure with a bound ligand is known. Antibody: UniProt predicts a signal peptide or a membrane-spanning region. PROTAC: ubiquitination databases record sites on it; its protein half-life has been measured.
Gene: Protein-coding gene on chromosome 15 (34,083,980 to 34,101,910, reverse strand). Ensembl gene ENSG00000134153.
Subcellular location: Endoplasmic reticulum membrane
Gene Ontology:
Molecular function: membrane insertase activity; protein binding; carbohydrate binding
Biological process: protein insertion into ER membrane by stop-transfer membrane-anchor sequence; tail-anchored membrane protein insertion into ER membrane
Cellular component: EMC complex; endoplasmic reticulum membrane; membrane
Genetic constraint (gnomAD): Loss-of-function variants: 4 observed, 24.39 expected, observed/expected ratio (o/e) 0.16, 90% interval 0.08 to 0.38. The upper end of that interval is the gene's LOEUF score, 0.38, which puts it in group 1 of 6, group 1 being the genes least tolerant of losing a copy. Missense variants: 221 observed, 310.55 expected, observed/expected ratio (o/e) 0.71, 90% interval 0.64 to 0.8. Synonymous variants: 106 observed, 118.1 expected, observed/expected ratio (o/e) 0.9, 90% interval 0.77 to 1.05.
Homologues: Orthologues: chimpanzee EMC7 (100% identical), macaque EMC7 (99% identical), guinea pig EMC7 (97% identical), mouse Emc7 (96% identical), dog EMC7 (95% identical), rat Emc7 (95% identical), rabbit EMC7 (93% identical), pig EMC7 (93% identical), tropical clawed frog emc7 (75% identical), zebrafish emc7b (67% identical), zebrafish emc7a (46% identical), Caenorhabditis elegans C35D10.1 (34% identical), and 1 more.
Diseases named in the same sentence as EMC7 in open-access papers:
EMC7 is named in the same sentence as 3 diseases in open-access papers, as found by Europe PMC text mining. Sharing a sentence is not in itself a finding about the gene and the disease. The quoted sentences say what the papers report.
virus infection (2 papers, 2016 to 2020). "In fact, our data suggest that other EMC subunits, particularly EMC3, EMC4, EMC5, EMC6, EMC7, and EMC10, may also exert roles in supporting virus infection." (PMID 28012275, 2016).
infection (1 paper, 2020). The state of being infected such as from the introduction of a foreign agent such as serum, vaccine, antigenic substance or organism. "Our data thus far suggest that EMC4 and EMC7 support LE-to-ER transport of SV40 in order to promote productive infection." (PMID 32111841, 2020). "We conclude that the disordered domain and LCR harbored within EMC7’s cytosolic domain mediate Rab7-binding required for ER-arrival of SV40 enabling productive infection." (PMID 32111841, 2020). "In sum, these findings suggest that EMC4 and EMC7 function as molecular tethers, juxtaposing the ER to the LE to enable efficient transport of SV40 from the LE to the ER essential for successful infection." (PMID 32111841, 2020). "Strikingly, we found that depletion of EMC4 or EMC7 blocked SV40 infection because the virus cannot reach the ER from the LE, a critical infection step; under this compromised condition, SV40 is trapped in the LE as expected." (PMID 32111841, 2020). "Indeed, we found that Stx18, an ER membrane SNARE essential in endosome-to-ER delivery of BK PyV16, binds to EMC4 and EMC7, and also plays an important role in sorting SV40 to the ER to promote infection." (PMID 32111841, 2020).
tumor (1 paper, 2025). "We observed significant downregulation of SOX7 expression in MM bone marrow tumor samples compared to normal bone marrow PC samples when expression levels of RPL37A or EMC7 housekeeping gene were used to obtain normalized expression of each sample." (PMID 40699642, 2025).